MPO (myeloperoxidase)
Diseases named in the same sentence as MPO in open-access papers (continued):
Sharing a sentence is not in itself a finding about the gene and the disease.
endothelial dysfunction (continued). "The positive MPO-LpPLA2 correlation within group I, and the negative correlation within group II, was likely caused by the more severe endothelial dysfunction of the patients in group II." (PMID 27928450, 2016). "Although the mechanism is unknown, it was reported that histones and myeloperoxidase, critical components of NETs, could be responsible for NETs-induced endothelial dysfunction." (PMID 26849138, 2016). "Additionally, MPO promotes endothelial dysfunction and apoptosis/detachment, promoting plaque rupture." (PMID 25371762, 2014). "Thus, MPO promotes inflammation and oxidative stress and contributes to endothelial dysfunction and plaque formation, rupture and ventricular remodeling following MI." (PMID 25371762, 2014). "NETs are able to induce endothelial dysfunction and NET-associated MPO retains its activity." (PMID 23691142, 2013). "Recent studies have shown that MPO plays an important role in endothelial dysfunction." (PMID 21234421, 2010). "However, high levels of myeloperoxidase on the examination day led to strongest effects on endothelial dysfunction." (PMID 19079718, 2008). "It has been suggested that DOX also induces endothelial dysfunctions, because it has been demonstrated in vivo that treatment with DOX caused oxidative stress and myeloperoxidase (MPO) activity." (PMID 17325706, 2007). "However, it remains unknown whether MPO released from leukocytes promotes endothelial dysfunction or if endothelial cells act as their own reservoir of MPO." (PMID 39456241, 2024). "Thus, the synergistic action of NADPH oxidase and MPO activation could be a pivotal event in NET-induced endothelial dysfunction and vascular damage." (PMID 38034546, 2023). "In addition, neutrophils can release pro- and anti-inflammatory cytokines through the myeloperoxidase pathway leading to endothelial dysfunction, increased microvascular permeability, tissue damage and have been identified to produce VEGF-A and D coordinating lymphangiogenesis." (PMID 34956972, 2021). "In addition, neutrophils could contribute to oxidative stress and endothelial dysfunction by releasing a large amount of myeloperoxidase, NADPH oxidase, and so on." (PMID 34869661, 2021). "Liberated MPO may penetrate the endothelium and accumulate extracellularly in the subintimal space, where the activity of MPO will reduce the half-life of nitric oxide, released from the endothelium, and thus counteract NO-dependent vasodilator mechanisms and contribute to endothelial dysfunction." (PMID 24707472, 2014). "Obesity promotes the accumulation of myeloperoxidase (MPO)-releasing myeloid cells within PVAT, and MPO levels correlate positively with body weight and endothelial dysfunction in both obese patients and animal models." (PMID 41528566, 2026). "We first looked at the role of MPO in oxidizing LDL-C, followed by its role in inflammation and endothelial dysfunction." (PMID 41226326, 2025). "However, in this study, we did not explore the association between MPO levels and other key factors involved in PE, such as endothelial dysfunction and oxidative stress, and this hypothesis remains to be proved." (PMID 40806204, 2025). "We identified inflammatory and endothelial dysfunction markers (ADAMTS-13, TNF-α, GDF-15, MIP-1β, VEGFA, MPO, and MIC-1) that cooperate in a common pathway and are increased in FD patients’ plasma samples." (PMID 38892211, 2024). "Myeloperoxidase (MPO), 15-lipoxygenase, and NADPH oxygenase (NOX), which are activated by endothelial dysfunction, are suggested to be responsible for this oxidative modification." (PMID 36829817, 2023). "MPO has been reported to contribute to the development of CAD through multiple pathways, including triggering endothelial dysfunction, activation of inflammatory responses and weakening of atherosclerotic plaques." (PMID 37405052, 2023).
endothelial dysfunction (continued). "Also MPO was reported to control eNOS activity and/or nitric oxide bioavailability by direct reaction of the MPO compound 1 (highly oxidized iron intermediate during the reaction cycle of peroxidases) with nitric oxide, thereby consuming the vasodilator and thereby inducing endothelial dysfunction." (PMID 36719770, 2023). "Markers of endothelial dysfunction (ICAM1, VCAM, VEGFR3, thrombomodulin) and inflammatory response (CRP, MPO) were also noted to progressively increase with rising altitude in both groups, more prominently so in ICs and has been reported earlier by us." (PMID 37384264, 2022). "Myeloperoxidase (MPO)-derived products released from activated neutrophils can mediate the inflammatory response and contribute to endothelial dysfunction." (PMID 32457656, 2020). "In a rat model, histology and staining for myeloperoxidase (MPO) activity revealed a significant accumulation of neutrophils in α-toxin A-challenged hearts concomitant with reduced cardiac contractility and endothelial dysfunction." (PMID 31565659, 2019). "Escin significantly ameliorated endothelial dysfunction (increased serum E-selectin and ICAM-1 and lung Wet/Dry ratio, decreased serum NO), and oxidative and inflammatory responses (increased serum MDA, MPO, IL-6 and TNF-α) (P < 0.05 or P < 0.01)." (PMID 28112272, 2017). "In our cohort of obese children and adolescents, several biomarkers of vascular injury and endothelial dysfunction, including PAI-1, sICAM-1, MMP-9, MPO and VEGF, were significantly and positively correlated with circulating endotoxin concentrations." (PMID 26819711, 2015). "Myeloperoxidase (MPO) activity is suggested to reduce the function of vascular nitric oxide, thereby contributing to endothelial dysfunction, although data in rodents are inconclusive." (PMID 24707472, 2014). "Recent research shows that MPO is an emerging biomarker to assess cardiovascular diseases (CVD) and endothelial dysfunction in vivo as human subjects with significantly lower risks of CVD were found to have less MPO activity and vice-versa." (PMID 25168993, 2014). "Myeloperoxidase (MPO) is involved in reactive oxygen species-induced tissue damage and the production of dysfunctional HDL, and can promote oxidative stress, inflammation, and endothelial dysfunction leading to the progression of chronic kidney disease." (PMID 40004147, 2025). "In addition, curcumin downregulates other inflammatory mediators, including MPO and MMP-9, while modulating nitric oxide metabolites, thereby targeting both inflammatory and oxidative pathways involved in endothelial dysfunction." (PMID 40868165, 2025). "Furthermore, myeloperoxidase (MPO) served as a critical mediator linking oxidative stress, inflammation, and endothelial dysfunction." (PMID 39497801, 2024). "In addition, there is a kind of pathophysiological cross talk between the eNOS inhibitor ADMA and MPO, in which ADMA activates neutrophils and the release of MPO that in turn suppresses DDAH (enzyme for breakdown of ADMA) and leads to endothelial dysfunction." (PMID 36719770, 2023). "In addition, it alleviated endothelial dysfunction, led to a decrease in serum E-selectin and ICAM-1, and decreased the level of pro-inflammatory cytokines IL-6 and TNF-α in the serum and MPO, as well as the MDA of the oxidative stress marker." (PMID 37371797, 2023). "Additionally, the MPO and MPO-catalyzed HOCI amplified high glucose-induced endothelial dysfunction in cell culture and rat aorta." (PMID 32536875, 2020). "The endogenous eNOS inhibitor asymmetric dimethyl arginine (ADMA) activates neutrophils and release of myeloperoxidase (MPO) leading to inhibition of dimethylaminohydrolases (DDAH), the enzyme catalyzing the breakdown of asymmetric dimethyl arginine (ADMA), and endothelial dysfunction." (PMID 32408480, 2020).
endothelial dysfunction (continued). "Furthermore, HOCl and another MPO oxidant—HOSCN—modify low density lipoprotein (LDL), thereby interfering with endothelial vasorelaxation and inducing endothelial dysfunction." (PMID 33081101, 2020). "The present study was designed to determine whether myeloperoxidase (MPO) mediates HC-induced endothelial dysfunction and the role of the PPARγ agonist pioglitazone (PIO) in attenuating endothelial dysfunction." (PMID 32190383, 2020). "Treatment with lipopolysaccharide (LPS; to enhance endothelial dysfunction) reduced responses to Ach in MPO−/− but did not affect responses in wild-type." (PMID 24707472, 2014). "However, beyond the observed abnormalities in adhesive molecules that indicate a pro-inflammatory state, there is little evidence available linking MPO and inflammation to endothelial dysfunction in PLWH." (PMID 41226326, 2025). "While completely inhibiting MPO activity with non-selective inhibitors may affect its antimicrobial activity, selectively targeting extracellular MPO shows promise in eliminating MPO-induced endothelial dysfunction without compromising its bactericidal effect." (PMID 38275657, 2024). "MPO is involved in CVD processes in many ways, contributing to the oxidation of LDL, the impairment of high-density lipoprotein (HDL) function, the reduction in nitric oxide (NO) bioavailability leading to endothelial dysfunction, and the activation of matrix metalloproteinases (MMPs)." (PMID 38275657, 2024). "Considering the strong relation between MPO and systemic endothelial function, it might also be speculated that systemic activation of leukocytes, particularly via secretion of MPO, is one mechanism by which AMI leads to systemic endothelial dysfunction." (PMID 28704420, 2017). "Since this endothelial dysfunction was found only in saphenous and not carotid arteries, which differ in respect to the EDHF component, it is possible that the influence of MPO deficiency on endothelial function may primarily relate to the EDHF response." (PMID 24707472, 2014). "Additionally, indirect evidence from a number of studies have demonstrated that MPO can exacerbate mechanisms that are known to be involved in TAA pathogenesis, such as damage to the ECM and DNA, activation of inflammatory signaling, and an increase in endothelial dysfunction." (PMID 33081376, 2020). "The mechanisms by which MPO may promote atherogenesis include conversion of LDL into more atherogenic oxidized particles (oxLDL), oxidative modification of apolipoprotein A-I that results in a dysfunctional HDL and reduction of EC nitric oxide availability resulting in endothelial dysfunction." (PMID 20158910, 2010). "The findingthat patients with MPO levels above median do not display more endothelialdysfunction, nor vascular stiffness might be an indication that the sequence:comorbidities, inflammation, oxidative stress, endothelial dysfunction,myocardial remodelling is not straightforward." (PMID 39077419, 2023). "It should be noted that there are other pathways independent of MPO leading to LDL oxidation, diminished bioavailability of NO, disturbed endothelial dysfunctions, or protein carbamylation." (PMID 33137905, 2020). "Also, after the WBC procedures, the observed decrease in myeloperoxidase activity may have a relationship with the reduction of inflammation and white blood cell activation, as well as LDL oxidation and nitric oxide consumption leading to endothelial dysfunction." (PMID 33371392, 2020). "Finally, obesity influences various signaling pathways and vasoactive mediators next to MPO that have not been investigated and might contribute to PVAT phenotype, expression profile, and endothelial dysfunction." (PMID 40252642, 2025).
Stroke (119 papers, 2010 to 2025). Sudden impairment of blood flow to a part of the brain due to occlusion or rupture of an artery to the brain. "Expression levels of NET-associated markers (H3cit, MPO and dsDNA) were measured in the serum of stroke patients." (PMID 41098728, 2025). "Elevated MPO levels are associated with worse stroke outcomes, while its inhibition has been shown to reduce oxidative damage, preserve BBB integrity, and mitigate neuronal injury." (PMID 40076473, 2025). "Our work has revealed an association between increased MPO activity, particularly in the early subacute phase post-stroke, and neuronal damage in aged mice." (PMID 39325942, 2024). "MPO has been implicated in the pathogenesis of stroke because it induces arterial wall damage through oxidation and its indirect impact on the integrity and functioning of blood vessels." (PMID 38654328, 2024). "While aging is an unmodifiable risk, by uncovering the connection between aging and MPO-related changes after stroke, new therapies can be developed to mitigate these adverse changes brought upon by aging." (PMID 39325942, 2024). "Of note, inhibition of MPO improved blood flow in a diabetic mouse model of hind-limb ischemia, while higher serum MPO levels were associated with increased risk of myocardial infarction or stroke in patients with PAD." (PMID 36979845, 2023). "Any association of a genetic MPO predictor with stroke and CAD phenotypes is fully attenuated when we further add in variants significantly associated in the present meta-analysis." (PMID 35504531, 2022). "In our disease prediction model, we replicate a previous association between an MPO genetic score and risk of both stroke and CAD." (PMID 35504531, 2022). "Overexpressions of inflammatory mediators like iNOS, NF-κB, and MPO suggested that the stroke caused a severe inflammatory response in the intestine, which was also accompanied by the time when the intestinal permeability increased." (PMID 33642941, 2021). "Accordingly, serum MPO levels are elevated in human stroke patients, and certain MPO genotypes are associated with increased brain infarct size and poor functional outcome in human cerebral ischemia." (PMID 33801397, 2021). "MPO has been implicated in many brain diseases, including stroke, Alzheimer’s disease, and multiple sclerosis." (PMID 33801397, 2021). "Degranulation products like matrix metalloproteinase-9 (MMP-9) and myeloperoxidase (MPO) are generally considered to be associated with the presence of hemorrhage and poor function outcomes after stroke." (PMID 34322078, 2021). "Ex vivo: Intracellular and serum MPO and NE were measured on days 0, 1, 3 and 5 post-stroke by either flow cytometry or enzyme-linked immunosorbent assay (ELISA) and compared to controls." (PMID 28732504, 2017). "MPO-generated oxidants play detrimental roles in causing brain damage after stroke which is effectively reduced by KYC." (PMID 27220420, 2016). "Further, increased serum MPO levels in stroke patients have been associated with white matter hyperintensity, a measure of stroke severity assessed from brain MRI scans." (PMID 27220420, 2016). "Furthermore, many studies have associated elevated MPO levels with high-risk factors such as metabolic syndrome, including increased body mass index and dyslipidemia, as well as stroke, diabetes, thromboembolism, and cardiovascular diseases." (PMID 41476244, 2025). "Additionally, MPO serves as a marker of inflammation and has been implicated in stroke development, while SOD is recognized as an antioxidant enzyme that protects against damage caused by free radical oxygen species (ROS)." (PMID 40076473, 2025). "Interestingly, tMCAO had a significantly higher MPO level in the ischemic cortex than the pMCAO model after stroke onset, indicating that perfusion increases MPO and associated oxidative stress." (PMID 39325942, 2024). "Concentrations of serum MPO are increased after IS and was associated with stroke severity." (PMID 37065487, 2023).
Stroke (continued). "One study of stroke‐free adults found that elevated MPO was associated with greater burden of WMH." (PMID 37475160, 2023). "Moreover, the reduction of plasma HMGB1 in thrombocytopenic mice was associated with a significant reduction in plasma MPO-DNA complexes 24 hours after stroke (136% ± 53.1% vs. 295.6% ± 128.1%)." (PMID 35358095, 2022). "A recent study also investigated the association between MPO levels and stroke risk." (PMID 36439687, 2022). "Of note, high expression of MPO was associated with ischemic stroke, and MPO inhibition had beneficial effects, suggesting that MPO may represent a therapeutic target in stroke." (PMID 36034148, 2022). "To determine whether the stroke-induced loss of intracellular MPO and the enhanced levels of MPO and NE in sera could be mediated by catecholamines, acetylcholine or dexamethasone, we determined the effect of each of the compounds in vitro." (PMID 28732504, 2017). "Many inflammatory indicators (amyloid A, CRP, matrix metalloproteinases, myeloperoxidase, phospholipase A2, and others) and some OS indicators (malondialdehyde, protein carbonyls, and NO metabolites) have been identified as risk markers for stroke severity and prognosis." (PMID 41153334, 2025). "However, when adjusting for clinical parameters (intravenous thrombolysis and stroke etiology) this association could be shown to be confounded (OR for favorable reperfusion per MPO-histone AU increase = 1.231 [0.778–1.950] crude OR = 1.159 [0.787–2.014]))." (PMID 38853210, 2024). "Additionally, proteases associated with NETs, such as MPO, affect post-stroke neurogenesis." (PMID 36892020, 2023). "In addition, a case-cohort study, which enrolled 2176 participants and evaluated the correlation between 13 plasma biomarkers and stroke risk over a median follow-up of 5 years, proved that MPO was a potential biomarker that was independently associated with stroke risk." (PMID 36439687, 2022). "While MPO is necessary for the immune system to combat pathogens, its excessive activation after a stroke can be detrimental." (PMID 41373489, 2025). "MPO, which damages the endothelial cells, is mostly produced by neutrophils and its expression occurs in areas of myeloid cell infiltration in MS and stroke." (PMID 40362673, 2025). "Plasma levels of H3cit and MPO-DNA complexes were increased 24 hours post-stroke induction and decreased following the treatment of NETs inhibitor." (PMID 41098728, 2025). "In the immunofluorescent staining of dura mater from stroke patients, there was a positive correlation between the expression of MPO marker and CD19 marker." (PMID 40313936, 2025). "Between roughly 18 and 72 h post-stroke onset, activated microglia and infiltrating immune cells, such as macrophages and neutrophils, generate ROS through enzymatic systems like myeloperoxidase and inducible nitric oxide synthase." (PMID 40507904, 2025). "Animal studies have demonstrated that MPO inhibition significantly improves post-stroke neurological outcomes, with a reported 60% increase in Hsp70+/NeuN + neuronal survival." (PMID 40777988, 2025). "Immunohistochemical analysis showed a higher positive expression for H3cit and MPO in the stroke group compared to the sham group, while the positive expression was decreased in the stroke+CI group." (PMID 41098728, 2025). "ELISA analysis demonstrated a marked elevation in the total content of the MPO-DNA complex in plasma samples from stroke patients compared to those from HD." (PMID 41098728, 2025). "TRG interacted with MPO by forming hydrogen bonds with N-acetylglucosamine (NAG), arginine (ARG), and tryptophan (TRP), thus conferring brain protection from MPO-mediated inflammation after stroke." (PMID 38542359, 2024). "MPO is considered a “high-risk” biomarker for patients with acute coronary syndrome (ACS), CAD, heart failure, hypertension, and stroke." (PMID 38978787, 2024).